LAIR1 (leukocyte associated immunoglobulin like receptor 1)
Diseases named in the same sentence as LAIR1 in open-access papers (continued):
Sharing a sentence is not in itself a finding about the gene and the disease.
ovarian carcinoma (continued). "Similarly, LAIR-1 expression was detected in the tumor cells of ovarian cancer tissues and epithelial ovarian cancer (EOC) cell lines but not in normal ovarian tissues." (PMID 40806280, 2025). "In addition, the expression of LAIR‐1 in solid tumors such as ovarian cancer, cervical cancer, and hepatocellular carcinoma surpasses that in adjacent normal tissues and is positively correlated with tumor grade." (PMID 35702880, 2023). "Our results indicate that a LAIR-1-based strategy may prevent or suppress the progression of ovarian cancer." (PMID 32628130, 2020). "In this study, we identified the LAIR-1 cDNA sequence of the ovarian cancer cells HO8910." (PMID 32628130, 2020). "We have demonstrated for the first time that LAIR-1 is involved in the regulation of the PI3K-AKT-mTOR pathway that regulates the cell proliferation, apoptosis and metabolism of normal cells and is implicated in many cancers, including ovarian cancer." (PMID 32628130, 2020). "Recently, over-expression of LAIR-1 has been found in some solid cancers, including ovarian cancer." (PMID 32628130, 2020). "Our findings suggest that LAIR-1 may suppress the growth of ovarian cancer cells by serving as a modulator that suppresses PI3K-AKT-mTOR directly or regulating protein synthesis at the translational level." (PMID 32628130, 2020). "We further explored whether PI3K-AKT inhibitor can reverse the effects from LAIR-1 in ovarian cancer cells by evaluating the growth of HO8910 cells treated with or without a PI3K inhibitor LY294002." (PMID 32628130, 2020). "We showed that LAIR-1 could suppress ovarian cancer cell growth both in vitro and in vivo via the PI3K-Akt-mTOR pathway." (PMID 32628130, 2020). "Furthermore, we investigated the molecular mechanisms in ovarian cancer cells, and studied the LAIR-1 antitumor activity and its mechanism in vivo." (PMID 32628130, 2020). "In the present study, we identified the LAIR-1 cDNA sequence of the ovarian cancer cells HO8910." (PMID 32628130, 2020). "The binding of ETS-2 to LAIR-1 promoter leads to high expression of LAIR-1, may suppress the development of ovarian cancer." (PMID 29915163, 2018). "In the ovarian cancer cell line HO8910, inhibition of LAIR1 expression was shown to promote in vitro cell proliferation, to increase clonogenicity during colony formation assays, and to favor the invasive properties of tumor cells." (PMID 36555775, 2022). "In our previous study, we cloned and sequenced the LAIR-1 cDNA of COC1, another ovarian cancer cell line expressing high level LAIR-1." (PMID 32628130, 2020). "Our previous study showed that LAIR-1 is highly expressed in COC1 and other ovarian cancer cells including HO8910, and its expression inhibits cell proliferation and invasion of the HO8910 cell line." (PMID 29915163, 2018). "We confirmed the effect of LAIR-1 on the malignant phenotypes of other ovarian cancer cells by stably overexpressing LAIR-1 in SKOV3, an ovarian cell line with lower level LAIR-1 expression, using a LAIR-1-lentivirus based on the cDNA sequence of LAIR-1 from HO8910 and COC1." (PMID 32628130, 2020). "The ongoing trial NCT05572684 using NC410 (the dimeric LAIR-2 protein fused to a human IgG1 Fc domain, see Chapter 4.1) in combination with the anti-PD1 pembrolizumab in MSS and low-microsatellite stable CRC or ovarian cancer may give some insights into the cooperation of conventional ICI and LAIR1." (PMID 40563506, 2025). "The differential expression pattern of LAIR-1 in tumors versus normal tissues does not contradict with our present results showing that overexpression of LAIR-1 suppresses cell growth and induces apoptosis in ovarian cancer." (PMID 32628130, 2020).
acute myeloid leukemia (10 papers, 2019 to 2025). Acute myeloid leukemia (AML) is a group of neoplasms arising from precursor cells committed to the myeloid cell-line differentiation. "Two independent studies by us and Müschen’s group using in vitro and xenograft experiments showed that LAIR1 deficiency retards development of acute myeloid leukemia (AML) and Philadelphia Chromosome positive acute lymphoblastic leukemia (Ph+ B-ALL)." (PMID 36211388, 2022). "If the cancer cells express LAIR1, as in acute myeloid leukemia, agonism is more likely to be effective, as demonstrated by a LAIR1 agonist antibody that induced cell death in leukemia stem cells in cell and xenograft models." (PMID 40829176, 2025). "C3 and LAIR1((INK4a))genes were both detected, which were shown to be related to acute myeloid leukemia." (PMID 31533352, 2019). "Bioinformatics analysis revealed that many different types of tumor tissues expressed LAIR1 at higher levels than those in their corresponding normal tissues, particularly in acute myeloid leukemia, esophageal cancer, brain tumor, renal clear cell carcinoma and thymoma." (PMID 37845206, 2023). "Given its expression on most immune cells, and its inhibitory properties and regulatory role, LAIR-1 is thought to be a potential therapeutic target for diseases including acute myeloid leukemia and other cancers, as well as inflammatory diseases such as fibrosis and arthritis." (PMID 32719788, 2020). "In line with our findings, LAIR-1 activation has been previously depicted to reduce the proliferation of myeloid leukemia cell lines and acute myeloid leukemia (AML) blasts." (PMID 40806280, 2025). "Recently, ITIM motif containing receptors LAIR1 and PirB were identified to support acute myeloid leukemia (AML) stem cell survival, highlighting the importance of those receptor types for LSC biology." (PMID 32684632, 2020). "Furthermore, the engagement of LAIR1 on primary acute myeloid leukemia (AML) can inhibit the proliferation induced by granulocyte monocyte-colony stimulating factor (GM-CSF)." (PMID 40563506, 2025).
breast carcinoma (9 papers, 2019 to 2025). "Our results are in line with a previous study reporting the association of LAIR-1 expression with luminal breast cancer." (PMID 40806280, 2025). "The results that showed that heparanase-1 co-expressed with phosphoinositide 3-kinase adapter protein 1, sialic acid-binding immunoglobulin-like lectin 7, and leukocyte-associated immunoglobulin-like receptor 1 are directed related with immune system evasion during breast cancer progression." (PMID 33053017, 2020). "On the other hand, the expression of LAIR1 has been detected in breast carcinoma (BC) and some BC cell lines such as SKBR3 (HER2+) and MDA-MB-231 (HER2-) but at very low levels in MCF7 and MCF10A." (PMID 40563506, 2025). "In bone recurrence of breast cancer, osteoblasts have been found to promote tumor metastasis and growth by inhibiting LAIR-1 signaling and inhibiting NK cells." (PMID 37511932, 2023). "Our study highlights the importance of LAIR-1 expression and the role of the immune microenvironment in breast cancer progression and worse clinical outcome." (PMID 33396670, 2020). "By interaction with collagen in ovarian and breast cancer, tumor-associated dendritic cells expressed the highly receptor CD305/leukocyte-associated immunoglobulin-like receptor-1." (PMID 31521169, 2019). "This study aimed to elucidate the biological and prognostic role of LAIR-1 in invasive breast cancer (BC)." (PMID 33396670, 2020). "Analysis of the TCGA database showed that the expression of genes HPSE, PIK3AP1, SIGLEC7, LAIR1, and CTSL have positive correlations according to the breast cancer subtypes." (PMID 33053017, 2020). "The remodeling of the TME targeting the collagen/LAIR1 interaction together with TGFβ and PDL1 revealed that the enhanced tumor infiltration and activation of CD8+ T cells could be detected in murine models of colon and mammary carcinoma." (PMID 40563506, 2025).
glioma (9 papers, 2008 to 2025). A benign or malignant brain and spinal cord tumor that arises from glial cells (astrocytes, oligodendrocytes, ependymal cells). "Although the effects of LAIR1 signaling on T cell exhaustion and suppression have been well explored, our findings suggest that LAIR1 is more closely associated with the immunosuppressive polarization of macrophages/microglia in gliomas." (PMID 37845206, 2023). "The bioinformatic analysis of single-cell RNA sequencing data showed that LAIR1 was better expressed in glioma cells and macrophages/monocytes but less in astrocytes, endothelial cells, neutrophils, and T cells present in human brain cancer tissues." (PMID 40563506, 2025). "Targeting the immune inhibitory receptor LAIR1 presents a novel therapeutic strategy for gliomas marked by collagen-rich microenvironments." (PMID 40076738, 2025). "Pan-cancer examination revealed a correlation between COL6A1 and LAIR1 expression and across glioma lineages." (PMID 38357919, 2024). "LAIR1+ immune cells were found to be enriched in regions of collagen, indicating a potentially previously unappreciated mechanism of glioma-mediated immune suppression." (PMID 38357919, 2024). "Although the immune IMvigor210 cohort was a BLCA immunotherapy cohort (n = 398), the predictive effect of LAIR‐1 expression in BLCA can still be explored to elucidate its significance in glioma." (PMID 35702880, 2023). "The expression and function of LAIR1 in various glioma cell types, and how these cells communicate to control the immunosuppressive microenvironment, should be further investigated." (PMID 37845206, 2023). "The expression of LAIR1 was found to be inversely correlated with the overall survival probability of patients with all WHO glioma grades (P < 0.0001), WHO grade II glioma (P = 0.034), WHO grade III glioma (P = 0.00023), and WHO grade IV glioma (P = 0.0036)." (PMID 37845206, 2023). "Our study showed that CCL5 induced by intrinsic LAIR1 expression in glioma cells plays an important role in microglia/macrophage polarization, although more research is needed to determine the relationship in other cell types." (PMID 37845206, 2023). "The in vivo growth of glioma cells with different LAIR1 expression was studied in nude mice using a subcutaneously transplanted tumor model." (PMID 37845206, 2023). "In this study, the poor prognosis of glioma patients and the malignant proliferation of glioma cells in vitro and in vivo were found to be closely correlated with LAIR1." (PMID 37845206, 2023). "This is the first study to analyze the expression of LAIR‐1 in a large sample of patients with glioma." (PMID 35702880, 2023). "Studies have shown that IL‐8 promotes glioma invasiveness primarily by promoting angiogenesis and cell migration, which suggests that LAIR‐1 participates an critical part in mediating tumor progression via IL‐8 in the glioma TIME." (PMID 35702880, 2023). "In glioma, we investigated that LAIR‐1 overexpression was interrelated with clinicopathologic features such as grade, IDH status, 1p/19q non‐co‐deletion, and MGMT, suggesting that LAIR‐1 overexpression participates a role in the malignant behavior of glioma." (PMID 35702880, 2023). "Meanwhile, we also confirmed that LAIR‐1 protein was overexpressed in glioma cell lines compared with normal glial cells (NHA)." (PMID 35702880, 2023). "The cell cycle and apoptosis were assessed to study the role of LAIR1 in the growth of glioma cells." (PMID 37845206, 2023). "This study uncovered a critical role for intrinsic LAIR1 in facilitating glioma malignant progression and demonstrated a requirement for LAIR1 and SHP2 to enhance FAK nuclear localization." (PMID 37845206, 2023). "The correlation between LAIR‐1 and the prognosis of glioma patients was poorly understood in terms of the correlation with the glioma microenvironment, and therefore the specific mechanism needs further study." (PMID 35702880, 2023).
glioma (continued). "Both univariate and multivariate Cox regression analyses indicated that LAIR‐1 overexpression is an independent adverse factor affecting the prognosis of glioma patients, which was also confirmed in two other validated cohorts." (PMID 35702880, 2023). "Our study revealed the critical role of intrinsic LAIR1 in promoting the malignant progression of gliomas and established the need for ITIMs/LAIR1 and PTP/SHP2 to promote the nuclear localization of FAK." (PMID 37845206, 2023). "The purpose of the present study was to comprehensively examine the mechanism of LAIR‐1 in the progression and prognosis of gliomas and determine its correlation with malignant clinical features." (PMID 35702880, 2023). "Using glioma samples from the GTEx database, Spearman correlation analysis of LAIR1 expression and macrophage markers was performed." (PMID 37845206, 2023). "Understanding the role of LAIR1 in glioma immunology is crucial because the majority of receptors harboring ITIMs are involved in immune system regulation." (PMID 37845206, 2023). "GL261 glioma cells stably overexpressing (LAIR1OE) or knocking down (shLAIR1) LAIR1 were successfully constructed to establish an orthotopic glioma model." (PMID 37845206, 2023). "RNA sequencing analysis was performed to further explore the mechanism by which LAIR1 promotes the malignant progression of gliomas." (PMID 37845206, 2023). "Specifically, LAIR1 partially contributes to the immunosuppressive glioma microenvironment by CCL5-mediated microglia/macrophage polarization." (PMID 37845206, 2023). "LAIR1 specifically supports in the immunosuppressive glioma microenvironment via CCL5-mediated microglia/macrophage polarization." (PMID 37845206, 2023). "Using the ESTIMATE algorithm, we discovered that stromal and immune scores in glioma patients gradually increases with the increasing expression of LAIR‐1." (PMID 35702880, 2023). "RT-PCR and Western blot were used to detect LAIR1 expression in six glioma cell lines (human U87, U251, T98G, and U138 cells, mouse GL261 cells, and rat C6 cells)." (PMID 37845206, 2023). "In the current investigation, we discovered that LAIR1 was significantly correlated with the malignant proliferation of glioma cells both in vitro and in vivo, as well as with the poor overall survival of glioma patients." (PMID 37845206, 2023). "LAIR1 expression was detected by immunohistochemistry in a human glioma tissue microarray encompassing 162 glioblastoma patient specimens (HBraG180Su01)." (PMID 37845206, 2023). "LAIR1 expression in the TME has been shown on M2 macrophages, neutrophils, and T regulatory cells in association with the presence of the lymphocyte-specific protein (LSP) 1 in a series of gliomas." (PMID 40563506, 2025). "Currently, there is a phase I trial of a LAIR1 antagonist in myeloid malignancies (NextCure NCT05787496) that could be considered as a new treatment for collagen-enriched gliomas." (PMID 38357919, 2024). "To date, however, there have been few studies examining the role of LAIR‐1 in glioma." (PMID 35702880, 2023). "Leukocyte‐associated immunoglobulin‐like receptor‐1 (LAIR‐1), is an immunosuppressive receptor, widely expressed by immune cells, but the part of LAIR‐1 in glioma progression remains unclear." (PMID 35702880, 2023). "LAIR1 expression was significantly higher in glioma tissues than in the adjacent normal tissues." (PMID 37845206, 2023). "However, the expression and function of LAIR1 in glioma have received little attention." (PMID 37845206, 2023). "Therefore, this study examined the intrinsic oncogenic effect of LAIR1 in glioma." (PMID 37845206, 2023). "In this study, we also showed that LAIR1 remarkably promoted the production of CCL5, TGFβ2, and IL33 in glioma cells, in a nuclear FAK-dependent manner." (PMID 37845206, 2023). "We also explored the effect of LAIR‐1 on the level of immune cell invasion as well as the TIME and evaluated the predictive performance of LAIR‐1 for immune infiltration in glioma." (PMID 35702880, 2023).
glioma (continued). "However, the intrinsic function of LAIR1 in gliomas remains unclear." (PMID 37845206, 2023). "However, the precise function of LAIR1 in gliomas remains unknown." (PMID 37845206, 2023). "Additionally, there was a positive correlation between LAIR1 mRNA expression and the WHO glioma grade." (PMID 37845206, 2023). "SHP2Q510E (PTP domain mutant) or FAKNLM (non-nuclear localizing mutant) significantly reversed the LAIR1-induced growth enhancement in glioma cells." (PMID 37845206, 2023). "Analyses of immunohistochemical images of gliomas indicated that the protein level of LAIR‐1 in glioma tissues was significantly higher than those in adjacent normal tissues." (PMID 35702880, 2023). "Furthermore, the analysis of LAIR1 expression in human U87, U251, T98G, and U138 cells, mouse GL261 cells, and rat C6 revealed that LAIR1 was found to be present in U251 and T98G glioma cell lines, but not in U87 or C6 glioma cells." (PMID 40563506, 2025). "Thus, we considered the possibility of LAIR‐1 as a new therapeutic target for LGG patients, as it could provide an important new basis and direction for immunotherapy in glioma patients." (PMID 35702880, 2023). "Second, although we found that LAIR‐1 expression was interrelated with patient prognosis and immune invasion in glioma, we could not prove that LAIR‐1 affects prognosis through immune invasion, which needs to be verified using different cell lines." (PMID 35702880, 2023). "Our results imply that, at least in glioma cells, LAIR1-induced FAK nuclear translocation has a greater effect on malignant glioma growth than FAK catalytic activity inhibition, emphasizing the importance of assessing LAIR1 expression levels when utilizing FAK inhibitors for cancer treatment." (PMID 37845206, 2023). "Although annexin V/PI staining revealed no influence of LAIR1 on in vitro apoptosis, TUNEL labeling revealed obvious in vivo apoptosis in shLAIR1 GL261 glioma tissues." (PMID 37845206, 2023).